IL18 (interleukin 18)
Diseases named in the same sentence as IL18 in open-access papers (continued):
Sharing a sentence is not in itself a finding about the gene and the disease.
cancer (continued). "Several lines of evidence suggests that in cancer the inflammasome is positively associated with characteristics such as elevated levels of IL-1β and IL-18, activation of NF-κB signaling, enhanced mitochondrial oxidative stress, and activation of autophagic process." (PMID 27206676, 2016). "As HCC is a typical inflammation-related cancer, these biologic effects of IL-18 might thus be implicated with HCC development, suggesting that abnormal expression of IL-18 could be associated with the pathogenesis of this disease." (PMID 26213495, 2015). "Stratified analyses of the -607C/A polymorphisms in IL-18 gene promoter with cancer risk." (PMID 24130810, 2013). "In addition, there are only one study and five studies investigating the association between -607C/A polymorphisms in IL-18 gene promoter and cancer risk among African and Caucasian population, respectively." (PMID 24130810, 2013). "Therefore, we performed a meta-analysis to derive a more precise estimation of the association to help us better understand the relationship between -607 C/A polymorphism of IL-18 gene promoter and risk of cancer." (PMID 24130810, 2013). "Therefore, we performed a meta-analysis to derive a more precise estimation of the association to help us better understand the relationship between -607 C/A polymorphism of IL-18 gene and risk of cancer." (PMID 24130810, 2013). "IL-18 is a proinflammatory cytokine that increases in the blood of the majority of cancer patients and that has been associated with disease progression and, in some cancer types, even with metastatic recurrence, poor clinical outcome and survival." (PMID 21569399, 2011). "Interleukin-12 (IL-12) and Interleukin-18 (IL-18), are a class of cytokines associated with the suppression of angiogenesis, production of interferon-gamma, induction of apoptosis in cancer cells, and the activation of cytotoxic T cells and natural killer cells." (PMID 38352036, 2024). "Indeed, IL-18 is associated with increased migration of cancer cells and metastatic activity." (PMID 37298187, 2023). "The anti-tumor role of inflammasomes has been extensively studied in colitis-associated cancer, showing that the secretion of IL-18 mediated by the NLRP3 inflammasome could protect enterocytes from early-stage colitis induced by dextran sulfate sodium (DSS) or azoxymethane (AOM)." (PMID 34298833, 2021). "Evidence suggest that IL-18 gene polymorphisms may be risk factors for several cancers." (PMID 24066061, 2013). "Hence, the -607C/A polymorphisms in IL-18 gene promoter may modify the susceptibility of cancers though changing the expression of IL-18 gene." (PMID 24130810, 2013). "To clarify the association between IL-18 gene promoter polymorphisms and cancer risk, we performed this meta-analysis by pooling eligible studies to calculate the estimate of overall cancer risk and evaluated influence of cancer types, ethnicity, source of controls and sample size." (PMID 24066061, 2013). "The multifaceted functions of IL-18 have been utilized in cancer treatment to reduce the phenomenon of immune escape of tumors." (PMID 41751464, 2026). "Exosomes derived from immune cells, epithelial cells, and cancer cells have been shown to enhance inflammasome activation, triggering the release of pro-inflammatory cytokines such as IL-1β and IL-18." (PMID 40141358, 2025). "Microglial and astrocytic activation, along with p38 MAPK, IL-18, and IL-1β signaling, play critical roles in the development of pathological pain induced by nerve injury, cancer, and inflammation in male animals." (PMID 41511304, 2025). "Recent advances have highlighted the potential of targeting inflammasome components such as sensor proteins (e.g., NLRP3, AIM2), adaptor proteins (e.g., ASC), caspase-1, and downstream cytokines IL-1β and IL-18—to modulate the immune response against cancer." (PMID 40155968, 2025).
cancer (continued). "Proteomics results showed that CCL5 and IL18 proteins exhibited the most significant increase in expression in the brain compared to other cancer types." (PMID 41155216, 2025). "Interleukin-18 (IL-18) is considered as a promising cancer therapeutic agent due to the ability of cytokines to inhibit cancer by enhancing natural killer (NK) cell and cytotoxic T cell responses." (PMID 41154589, 2025). "The abundant production of 1O2 significantly activates caspase‐3, inducing the release of N‐GSDME, which subsequently triggers pyroptosis in cancer cells and the release of pro‐inflammatory cytokines IL‐1β and IL‐18." (PMID 41117183, 2025). "Specifically, cytokines like TNF-α, IL-6, IL-18, IL-1β, and INF-γ are implicated in cancer cachexia, promoting elevated energy expenditure, reduced appetite, and skeletal muscle degradation." (PMID 39996717, 2025). "Prostate cancer is characterized by high levels of IL-1β, IL-18, IL-6, and MIC-1/GDF-15 that are clinically relevant for this association with the risk of carcinoma and the prognosis of established cancer." (PMID 41560727, 2025). "Interleukin‐18 (IL‐18) is present in areas of persistent inflammation, across a range of autoimmune conditions, within diverse cancer types, and amid numerous infectious disease scenarios." (PMID 40453734, 2025). "IL-33 and IL-18 have been identified as the signalling mediators involved in cancer development and progression." (PMID 40247153, 2025). "After exposure of BCC lines for 2 h following pretreatment of eNK cells with IL-18/-21, we performed a washing step and measured the number of viable cancer cells after 48 h." (PMID 38548803, 2024). "Studies have shown increased concentrations of multiple cytokines, including interleukin 6, TNFα, interleukin 8, the cytokines MIF, TGFβ, interleukin 10 and interleukin 18 in patients with cancer." (PMID 39020272, 2024). "Although conflicting effects on cancer progression have also been described for IL18 and PPARγ, both can promote M2-like TAM differentiation, reversible by caspase-1 inhibition." (PMID 39353903, 2024). "Many cytokines, including GM-CSF, IL-7, IL-12, IL-15, IL-18, and IL-21, have entered clinical trials for people with advanced cancer, while the FDA has approved interferon-alpha and IL-2." (PMID 38360737, 2024). "IL-1β is a potent inflammatory cytokine affecting dendritic cells (DCs), NK, and T cells, whereas IL-18, with its ability to activate NK and T cells, has shown promise in preclinical cancer immunotherapy studies." (PMID 39737979, 2024). "Pyroptosis, as a form of lytic cell death, amplifies the release of mature interleukin-1 (IL-1) and interleukin-18 (IL-18), potentially influencing the development of cancer." (PMID 38392321, 2024). "Many cytokines, including GM-CSF, IL-7, IL-12, IL-15, IL-18, and IL-21, have entered clinical studies for people with advanced cancer." (PMID 38360737, 2024). "Accordingly, it is crucial to comprehend the processes governing the regulations of IL‐18 and IL‐18BP in cancer and microbial infections." (PMID 39188114, 2024). "On the other hand, it was shown in another study that the oral treatment of Phellinus igniarius extract at doses of 250 and 500 mg/kg significantly elevated IL-18 levels in mice implanted with Sarcoma 180 cancer cells." (PMID 39619199, 2024). "In particular, the mechanism of action of IL-18 in cancer progression involves hypoxia, which induces the transcription and secretion of IL-18, followed by the expression of hypoxia-inducible factor-1α (HIF-1α)." (PMID 39451257, 2024). "When treated with a relatively low dose of RP116 (MOI of 10) and IL-18/-21-pretreated eNK cells (E:T ratio of 0.25:1), the combination treatment showed the lowest number of viable cancer cells in both cell lines." (PMID 38548803, 2024). "Recent studies have primarily focused on the involvement of IL‐18 and IL‐18BP in the regulation of immune responses in cancer and microbial infections." (PMID 39188114, 2024).
cancer (continued). "Leptin can also promote the expression and secretion of IL-18 in TAMs through NF-κB/NF-κB1, thereby fostering the expression and proliferation of cancer cells through the PI3K-AKT/ATF-2 pathway." (PMID 39192979, 2024). "In certain types of cancer, IL-18 has been shown to be anti-tumorigenic and to enhance immunotherapy and chemotherapy." (PMID 39769266, 2024). "Here the authors report the characterization of the STING agonist IMSA101, showing that STING-induced IL18 secretion enhances CAR-T activity in preclinical cancer models." (PMID 38730243, 2024). "In contrast, with a higher dose of RP116 (MOI of 100) and IL-18/-21-pretreated eNK cells (E:T ratio of 1:1), the combination treatment showed low cancer cell viability (14% in HT-1376, 6% in 253J-BV)." (PMID 38548803, 2024). "IL-18, recognized as a checkpoint, is an attractive target in one of the most advanced therapies for cancer, CAR-T." (PMID 39769266, 2024). "In stark contrast to the development of immunotherapies that block IL-1ꞵ in cancer treatment, many cancer immunotherapies are being designed that promote IL-18 signaling due to its beneficial antitumor effects." (PMID 38391959, 2024). "By stimulating interleukin-18 (IL-18) and interleukin-8 (IL-8) production from M2 macrophages, it mediates the crosstalk between cancer cells and other cells in the TME." (PMID 39040042, 2024). "IL-18, as a single agent in cancer therapy, exhibits poor pharmacokinetics and an overall lack of efficacy." (PMID 39769266, 2024). "Pyroptosis triggers immune responses in cancer cells via two major pathways: the secretion of inflammatory cytokines IL-1β and IL-18 activated by caspase and the release of HMGB1 and ATP following pyroptotic cellular rupture." (PMID 39398428, 2024). "In some instances, IL-1β and IL-18 also contribute to the survival of the cancer cells, and that helps them spread to other organs by modulating the epithelial-to-mesenchymal transition (EMT)." (PMID 39769450, 2024). "Therapy with GLP-1 RA reduced ferroptosis and systemic/myocardial levels of NLRP-3, MyD88, IL-1, IL-6 and IL-18, supporting their use in cancer patients treated with anthracyclines and ICIs." (PMID 39457081, 2024). "Third, no cytokines were statistically significantly associated with cancer risk or subtypes after Bonferroni correction, including six inflammatory factors with suggestive correlations - Eotaxin, SCF, IL-1β, VEGF, IL-18, and IP-10." (PMID 38957317, 2024). "IL-18 was also described as an immune checkpoint in cancer treatments such as CAR T cell therapy and anti-PD-1 therapy." (PMID 39769266, 2024). "Considering the role of IL18 in cancer, we also discuss the current literature and potential mechanisms of differentially expressed cancer-related genes." (PMID 38139000, 2023). "For example, butyrate is reported to induce IL-10 and IL-18 production through GPR109A to inhibit colonic inflammation and inflammation-associated cancers." (PMID 37238867, 2023). "Preclinical studies point towards strong antitumor efficacy of the P2RX7/IL-18 axis in several types of cancers." (PMID 37298187, 2023). "In any case, the studies have been consistent in showing that IL-18 release in an immune-P2RX7-dependent manner is highly antitumoral, and suggesting that boosting the P2RX7/IL-18 pathway is promising for several types of cancer." (PMID 37298187, 2023). "The effector cytokines, IL-1β and IL-18, released during chronic inflammation, induce cancer cell proliferation in a paracrine and autocrine manner." (PMID 37891577, 2023). "Previous studies have established that both IL-1β and IL-18 play essential roles in fostering cancer cell metastasis." (PMID 38066523, 2023). "The Gasdermin (GSDM) family member genes NLRP3, NLRC4, NLRP1, AIM2, IL-1β, and IL-18 are linked to TIME, and the immunosuppressive microenvironment can be overcome by targeted pyroptosis therapy in cancers." (PMID 36882663, 2023).
cancer (continued). "The benefits of adoptive NK transfer include the improvement of anti-cancer responses of autologous NK cells through cytokine stimulation, e.g., IL-2, IL-12, IL-15, IL-18 and IFN-γ type I, which enhance the function and proliferation of natural killer cells." (PMID 36980527, 2023). "AhR further interacted with the promoter of TMPRSS2, thereby upregulating TMPRSS2 and IL18 expression to promote cancer progression." (PMID 36975376, 2023). "Previous studies have indicated that the activation of NLRP3 inflammasome can contribute to cancer progression by releasing inflammatory cytokines such as IL-1β and IL-18." (PMID 38026959, 2023). "IL18 is considered to be an inflammatory factor which plays a crucial immune regulation role in cancers." (PMID 37698530, 2023). "IL-18 is related to cancer onset and patient clinical outcomes through its ability to promote the activation of immune cells such as NK and T cells, inducing IFN-γ secretion and driving enhanced cytotoxic activity." (PMID 37885032, 2023). "Because of the inflammasome complexes' overproduction of IL-1 β and IL-18, a chronic inflammatory state is established, which aids in cancer." (PMID 37715239, 2023). "Following cancer cell death, several cytokines (i.e., IL-1, IL-6, IL-8, IL-12, IL-18) and chemokines such as CCL5 are released that lead to the mobilization and activation of additional immune cells, further contributing to the host’s defense against cancer." (PMID 37371127, 2023). "The significance of IL18RAP in cancers has received little research despite being a significant factor of IL18 signaling." (PMID 37698530, 2023). "Since the readout activity of NLRP3 is the release of mature inflammatory cytokines, we will focus in the next section on the role of IL-1β and IL-18 in cancer progression." (PMID 37298187, 2023). "Clinically, IL-1β, IL-18, IL-6, and MIC-1/GDF-15 levels are associated with the risk of carcinoma and the prognosis of established cancer." (PMID 37715239, 2023). "Interleukin-18 (IL-18) is a key cytokine responsible for immune response and involves in the process of cancer development." (PMID 36797662, 2023). "In this study, it was confirmed that IL-18 is regulated by RanBP1, and that cancer stem cells (CSCs) and the epithelial−mesenchymal transition (EMT) phenomenon are regulated by IL-18." (PMID 37047826, 2023). "Although the many roles of IL18 have been revealed through basic and clinical studies (e.g., as a cancer therapy), there have been few clinical trials." (PMID 38139000, 2023). "As IL-1β was discovered long before IL-18, its role in inflammation and cancer progression has been vastly studied and well-reviewed." (PMID 37298187, 2023). "The exact role of IL-18 in cancer progression warrants further investigation to determine (i) the cancer type, (ii) the cell source and (iii) its activity (free unbound IL-18)." (PMID 37298187, 2023). "When activated, the NLRP3 inflammasome stimulates the release of pro-inflammatory cytokines IL-1β and IL-18, which promote the progression of cancer." (PMID 37345134, 2023). "In its early phases, the immune system can suppress it via NLRP3 inflammasome activation and IL-18 secretion which in turn can trigger the NK cells to exert their cytotoxic potential against cancer cells." (PMID 36763290, 2023). "For multivariable analysis, the distribution of IL-18 in the immune-stromal cells and carcinoma cell embolus was assessed by the Cox proportional-hazards model." (PMID 38031068, 2023). "IL-18 is a pleiotropic pro-inflammatory cytokine belonging to the IL-1 superfamily, playing an essential role in inflammatory responses and cancers." (PMID 35464869, 2022). "Quite many investigations have detailed that IL‐18 expression level is positively correlated with disease progression in different types of cancers." (PMID 34196131, 2022).
cancer (continued). "On the other hand, IL-18 is highly expressed in several cancers, within its microenvironment IL-18BP acts as a barrier for the cancer niche not only by increasing Treg, but also by attenuating natural killer (NK)-mediated killing." (PMID 35885055, 2022). "A previous study showed that IL‐18 plays both pro and anti‐inflammatory roles in cancer progression." (PMID 34196131, 2022). "Numerous approaches using vaccination with IL-12 single-transduced DCs and IL-18 single-transduced DCs in cancer immunotherapy have been reported." (PMID 35372586, 2022). "This unexpected lower efficiency is mostly due to the production of IL-18BP in the cancer microenvironment that neutralizes exogenous IL-18, as well." (PMID 35885055, 2022). "IL‐18 is a cytokine that manipulates both pro and anti‐cancer characteristics depending upon the host condition." (PMID 34196131, 2022). "Activation of pyroptosis leads to the release of the inflammatory mediators IL-1 and IL-18, which can contribute to the development of cancer in a number of ways." (PMID 35633405, 2022). "Monoclonal antibodies, Epstein–Barr virus infection, cancer pathways, immunoglobulins, and the IL-18 signalling pathway were the most enriched and significant discoveries from late stages." (PMID 35884999, 2022). "The main purpose of our research was to develop and characterize the antitumor activity of a novel cancer vaccine, based on DCs transduced for the simultaneous production of IL-12 and IL-18." (PMID 35372586, 2022). "On the other hand, inflammatory mediators IL-1 and IL-18, released by the activation of pyroptosis, can promote the progression of various cancers." (PMID 35659304, 2022). "The biological processes involved mainly included pathways related to cancer, the IL-18 signaling pathway, and response to inorganic substances." (PMID 36059967, 2022). "We found that the presence of DC/IL-18 + IL-12/TAg induced an increase in cytotoxicity of spleen cells against MC38 cancer cells." (PMID 35372586, 2022). "53, while the expression level of Interleukin-18 was enhanced, inhibiting the proliferation of cancer cells." (PMID 36017495, 2022). "Among various cytokines, IL‐18 has emerged as a major player in inflammation and progression of different types of cancers." (PMID 34196131, 2022). "Other approaches to enhance the antitumor activity of IL-18 include combining it with chemotherapy and other immune therapeutics (monoclonal antibodies,other cytokines, cancer vaccines)." (PMID 35529882, 2022). "Pyroptosis-based cells exhibited the activation of caspase-8/3, the release of inflammatory factors (IL-18, IL-1β, etc.)and a strong relationship to inflammation, immunity and cancer." (PMID 36501209, 2022). "Despite the established role of inflammasome pathway in the orchestration of an inflammatory response, through release of pro-inflammatory cytokines IL-1β and IL-18, its role in cancer development, progression, and immunotherapy response remains contradictive." (PMID 36032139, 2022). "The results showed that the expression levels of IL-6, IL18 and GSDME were positively associated with these compounds, while CASP4 was positively correlated with sensitivity to 26 cancer drugs." (PMID 35246158, 2022). "Despite the biological activity of IL-18 seen in early studies, IL-18 monotherapy had limited efficacy in cancer patients." (PMID 35529882, 2022). "Notable increases in the fold change of circulating levels of IL-2, IL-15, and IL-18 were also documented following SBRT and immunotherapy; these cytokines have been associated with promising cancer immunotherapeutic approaches." (PMID 35055015, 2022). "Elevated levels of IL-18 in the serum of patients with various forms of cancer correlate with the progression of the disease and the development of metastasis." (PMID 36286034, 2022).